LINC00870 (long independently transcribed non-coding RNA 870)
Gene: Long non-coding RNA gene on chromosome 3 (72,151,215 to 72,257,529, forward strand). Ensembl gene ENSG00000243083.
Diseases named in the same sentence as LINC00870 in open-access papers:
LINC00870 is named in the same sentence as 1 disease in open-access papers, as found by Europe PMC text mining. Sharing a sentence is not in itself a finding about the gene and the disease. The quoted sentences say what the papers report.
Stroke (1 paper, 2023). Sudden impairment of blood flow to a part of the brain due to occlusion or rupture of an artery to the brain. "Non-coding genes LINC00870, LINC01206, LINC01287, and LINC02073 are mainly more highly expressed in stroke patients, so they are upregulated." (PMID 37508918, 2023).